SPAST (spastin)
Diseases named in the same sentence as SPAST in open-access papers (continued):
Sharing a sentence is not in itself a finding about the gene and the disease.
autosomal dominant pure HSP (3 papers, 2020 to 2024). "SPAST gene mutation is the most common cause of autosomal dominant pure HSP (SPG4), although in-depth studies of larger patient cohorts have also associated gene mutation with more complex forms of HSP with bulbar dysfunction, and sensory and lower motor neuron signs." (PMID 31848577, 2020). "Among these, Spastic paraplegia type 4 (SPG4), caused by variants in the SPAST gene, represents the most prevalent form of autosomal dominant pure HSP." (PMID 39139823, 2024).
glioblastoma (3 papers, 2015 to 2023). The most malignant astrocytic tumor (WHO grade IV). "Microtubule-severing protein Spastin has been shown to co-localize with actin in migratory glioblastoma cells and is linked to glioblastomas’ migration and invasion capacity." (PMID 36766769, 2023). "Spastin, which has been reported to increase in expression in correlation with the invasion capacity of glioblastoma tumor cells, causes severe microtubule loss when overexpressed in dividing cells." (PMID 36766769, 2023). "Of note, increased spastin levels have been linked to increased malignancy and invasiveness of glioblastomas." (PMID 26691836, 2015). "Spastin has recently been linked to glioblastoma cell motility, as it was shown that the level of M87-Spastin increased in correlation with glioblastoma cell invasion capability, and Spastin was found to be co-localized with actins in migratory glioblastoma cells." (PMID 36766769, 2023). "Indeed, Spastin’s orientation to the cell periphery would result in glioblastoma cells having a high migration and invasion ability, causing them to be highly aggressive tumors." (PMID 36766769, 2023). "High-grade malignancy glioblastomas were linked to increased expression of spastin." (PMID 26691836, 2015). "Here, we identified Pin1 as a novel interaction partner of Spastin and showed that this interaction is required for transient co-localization of Spastin with actin filaments to enhance migration and invasion of T98G glioblastoma cells." (PMID 36766769, 2023). "We also performed the pull-down analysis with the wild-type and mutant Spastin constructs expressing T98G glioblastoma cells to confirm the involvement of Pin1 in the temporary alteration of Spastin’s localization in T98G cells." (PMID 36766769, 2023). "Real-time cell migration analysis was employed to investigate if the orientation of Spastin to actin filaments as a result of its interaction with Pin1 plays an active role in the migration and invasion abilities of T98G glioblastoma cells." (PMID 36766769, 2023). "Here, we demonstrated that Spastin plays an active role in glioblastoma migration by showing a reduced migratory potential of T98G glioblastoma cells using real-time cell analysis (RTCA) in Spastin-depleted cells." (PMID 36766769, 2023). "However, high proliferation ability and the absence of cellular death of glioblastoma cells in the presence of high levels of Spastin is possibly due to phosphorylation of Spastin because of the increased EGFR activity in glioblastoma cells." (PMID 36766769, 2023). "Since our real-time cell analyses clearly show that the interaction between Spastin and Pin1 promotes the migration and invasion capacities, this interaction might be a therapeutic target for glioblastoma treatment." (PMID 36766769, 2023). "Additionally, the decrease in T98G cell migration caused by the silencing of Spastin indicates that the MBD region of the endogenous Spastin is likely to be present in the phosphorylated form in T98G glioblastoma cells." (PMID 36766769, 2023). "Since Pin1 is known to alter the subcellular localization of its target proteins, in this study, we investigated whether Pin1 plays a role in the transient localization change in Spastin in migrating T98G glioblastoma cells." (PMID 36766769, 2023). "Furthermore, we discovered that endogenous Spastin is directed to actins in T98G glioblastoma cells upon Pin1 overexpression, which is comparable to EGF treatment." (PMID 36766769, 2023). "Since T98G glioblastoma cells mainly express the M87-Spastin isoform, to analyze the role of M87-Spastin in detail and compare the isoforms, we cloned the wild-type (SpastinM87) and mutant (SpastinM87_mutA and SpastinM87_mutD) M87-Spastin constructs expressing only the M87-Spastin isoform." (PMID 36766769, 2023).
glioblastoma (continued). "In conclusion, our findings demonstrated that M87-Spastin has a role in the T98G glioblastoma cell migration and invasion processes, and this involvement is controlled by its shift from microtubules to actin filaments via its interaction with Pin1 through its MBD." (PMID 36766769, 2023). "All these findings indicate that M87-Spastin could contribute to the migration and invasion ability of T98G glioblastoma cells only if it is directed to actin filaments after interacting with Pin1 owing to its phosphorylation in the MBD region." (PMID 36766769, 2023). "However, the effectiveness of Spastin in glioblastoma migration and the molecular mechanism underpinning the orientation of Spastin towards actin filaments remain unknown." (PMID 36766769, 2023). "Moreover, because this interaction is unlikely to occur in healthy glial cells due to the low expression of Spastin and Pin1, targeting this interaction may only influence cancer cells; hence, targeting this interaction may be a safe alternative for improving glioblastoma therapy." (PMID 36766769, 2023). "Given this, developing a bio-mimetic medication that may interfere and disrupt Spastin’s MBD interaction with Pin1 may be a critical step toward treating and preventing the recurrence of glioblastoma tumors." (PMID 36766769, 2023). "In this study, we demonstrated that Spastin plays an active role in cell migration by using real-time migration analysis of T98G glioblastoma cells in the presence and absence of Spastin, establishing for the first time a relationship between Spastin and cell migration." (PMID 36766769, 2023).
microcephaly (3 papers, 2008 to 2025). A congenital or acquired developmental disorder in which the circumference of the head is smaller than normal for the person's age and sex. "Notably, mutations in genes encoding tubulins or functionally related proteins such as CIT-K and spastin trigger the onset of neurodevelopmental disorders, including microcephaly." (PMID 35922843, 2022).
motor neuron degeneration (3 papers, 2013 to 2021). "The mutations in these SPG3A and SPG4 cases and their HSP-associated proteins atlastin-1 and spastin, respectively, result in dysfunctional axonal transport with consequently corticospinal motor neuron degeneration." (PMID 33716937, 2021). "In addition, various syndromes of motor neuron degeneration are caused by mutations in other genes such as Progranulin/GRN, Angiogenin/ANG, CHMP2B, Spastin/SPAST, PRPH, VAPB, and Alsin/ALS2." (PMID 25955410, 2015).
depression (2 papers, 2010 to 2019). "All patients with pathogenic mutations in the SPAST gene exhibited progressive spastic paraparesis, with 8 patients, including the sporadic patient case, also experiencing bladder disturbances (66%) and 9 having mild or moderate degree of depression (75%)." (PMID 20214791, 2010).
Encephalopathy (2 papers, 2021 to 2026). Encephalopathy is a term that means brain disease, damage, or malfunction. "This study provides novel insights into the clinical manifestations, molecular, and cellular mechanisms associated with biallelic variants in the SPAST gene among individuals presenting with moderate‐to‐severe early‐onset encephalopathy, spastic tetraparesis, and neuronoaxonal involvement." (PMID 41000004, 2026). "We provide the first evidence of biallelic inheritance in SPAST‐related disorders, supported by functional analysis, expanding the clinical spectrum to include moderate‐to‐severe early‐onset encephalopathy." (PMID 41000004, 2026). "Here, we present five individuals from three unrelated families with biallelic SPAST variants, all exhibiting early onset complex HSP characterized by encephalopathy with diverse severity, spasticity, neuroaxonal involvement, and central nervous system neuroimaging abnormalities." (PMID 41000004, 2026).
Fanconi anemia (2 papers, 2022 to 2025). Fanconi anemia (FA) is a hereditary DNA repair disorder characterized by progressive pancytopenia with bone marrow failure, variable congenital malformations and predisposition to develop hematological or solid tumors. "Our finding of the deletion occurring between AluY pairs is consistent with this observation, and similar mechanisms have been observed in several diseases, including Fanconi anemia, SPAST, and AAAS genes." (PMID 40033291, 2025). "Each of these four genes is mutated in a hereditary disease/syndrome, which are the hereditary breast and ovarian cancer syndrome (BRCA1), α-gammaglobulinemia (BTK), Fanconi anemia (FANCA), and spastic paraplegia 4 (SPAST)." (PMID 36075911, 2022).
glioma (2 papers, 2013 to 2019). A benign or malignant brain and spinal cord tumor that arises from glial cells (astrocytes, oligodendrocytes, ependymal cells). "This includes the effect of the observed overexpressions, like spastin, vimentin, nestin, actin cross-linkers, etc., on migration and the underlying mechanisms, but also how migration associated signaling is altered in glioma and whether this can be used for specifically targeting glioma migration." (PMID 31003495, 2019).
learning disabilities (2 papers, 2017 to 2020). "A recent study analyzing mutations in the human spastin gene reported patients with learning disabilities and memory impairments." (PMID 32866173, 2020). "In our cohort, we report 4.7% of patients with genetically diagnosed spastin mutation and learning disabilities and 3.5% of seizures." (PMID 28572275, 2017).
optic atrophy (2 papers, 2021 to 2023). A disorder characterized by loss of optic nerve fibers. "Seven patients out of 33 sporadic HSPs (21.2%) received a genetic diagnosis: five harbored mutations in SPAST, one case had biallelic variants in SPG7, and a young woman manifesting with HSP + early onset optic atrophy harbored a nonsense variant in OPA1." (PMID 33669240, 2021).
psychosis (2 papers, 2021 to 2022). "Currently, there are over 80 genetic subtypes of SP resulting in a spectrum of associated phenotypes, including the SPAST gene in SPG4, a microtubule-associated gene, which is associated with an increased rate of schizophrenia and psychosis in the affected individuals." (PMID 33597717, 2021).
African trypanosomiasis (1 paper, 2022). "PBS and CLR test approaches have both indicated PSGs including IL12A, LAMA4, MYD88, SPAST and BOLA to confer resistance mechanisms towards the African trypanosomiasis and tick infestation." (PMID 35428239, 2022).
alopecia (1 paper, 2022). Hair loss usually from the scalp. "Subject II.3 presented type 4 spastic paraplegia with an intragenic heterozygous deletion of the SPAST gene (2p22.3), anti-phospholipid syndrome with suspected neurological involvement, bilateral retinal detachment, endometriosis, recurrent oral ulceration, alopecia, and splenomegaly." (PMID 36123612, 2022).
atherosclerosis (1 paper, 2020). A disease characterized by the build-up of fatty material and calcium deposition in the arterial wall resulting in partial or complete occlusion of the arterial lumen. "SPAST was identified as a target of miR-33 and a potential therapeutic target for the treatment of atherosclerosis." (PMID 33192306, 2020).
Azoospermia (1 paper, 2023). Absence of any measurable level of sperm,whereby spermatozoa cannot be observed even after centrifugation of the semen pellet. "Here we reveal that the microtubule-severing protein spastin is also essential for multiple aspects of male germ development, and that its loss is ultimately incompatible with sperm production (azoospermia), owing to compromised meiosis followed by a catastrophic loss of nuclear structure." (PMID 36971361, 2023).
cerebellar degeneration (1 paper, 2021). Degeneration of the cerebellum. "The present study discovered an unidentified convergence of SNX14 and spastin in mitochondrial transport and dysfunction and demonstrated the possibility of the restoration of mitochondrial function by targeting of the pathway in the treatment of cerebellar degeneration." (PMID 34691693, 2021).
cerebral palsy (1 paper, 2026). A group of disorders affecting the development of movement and posture, often accompanied by disturbances of sensation, perception, cognition, and behavior. "We describe five individuals from three unrelated families who meet the clinical criteria for cerebral palsy and carry biallelic SPAST variants." (PMID 41000004, 2026). "In conclusion, our study advances the understanding of the phenotypic spectrum related to SPAST variants, supporting their inclusion within the cerebral palsy (CP) spectrum due to early‐onset symptoms and an extended phenotype beyond muscular spasticity." (PMID 41000004, 2026).
cervical cancer (1 paper, 2019). A primary or metastatic malignant neoplasm involving the cervix. "In cervical cancer cells two isoforms of spastin protein encoded by SPG4 harboring the same missense mutation bind and bundle different subsets of microtubules, which can be stabilized by increasing the level of acetylated tubulin." (PMID 30886064, 2019).
generalized dystonia (1 paper, 2025). "Interestingly, one patient with early‐onset generalized dystonia harbored two known likely pathogenic variants in different genes (TOR1A:p.Arg288Gln and SPAST:p.Glu418del)." (PMID 40533913, 2025).
pressure ulcers (1 paper, 2023). "Severe pressure ulcers developed in two patients with ALD; patient 1 and his mother had a variant in the SPAST and ABCD genes." (PMID 37081902, 2023).
prostate tumors (1 paper, 2016). "Protein expression levels of all three analyzed autoantigens, SPAST, STX18 and SPOP were significantly deregulated either in primary prostate tumors and/or in late, castration-resistant tumor stages." (PMID 26863016, 2016).
Sjögren's syndrome (1 paper, 2014). "Spastin interacts in cells with the NA14 protein, a major target for auto-antibodies in Sjögren's syndrome (nuclear autoantigen 1; SSNA1)." (PMID 25390646, 2014). "Spastin interacts with the centrosomal protein NA14, a major btarget for auto-antibodies in Sjögren's syndrome (nuclear autoantigen 1, SSNA1)." (PMID 25390646, 2014).
status epilepticus (1 paper, 2019). Status epilepticus is defined as a continuous seizure lasting more than 30 min, or two or more seizures without full recovery of consciousness between any of them. "Spastin is also found to be mutated in autosomal dominant pure HSP, and its expression level was decreased in status epilepticus and TLE mouse models." (PMID 31772151, 2019).
tauopathies (1 paper, 2015). "There is one report on a mutation of spastin (exon 10, R424G), in which authors also looked for other brain pathologies and identified Lewy bodies and tauopathy." (PMID 26691836, 2015). "This indicates that spastin or upstream regulators of spastin activity could serve as therapeutic targets for AD and related tauopathies." (PMID 26691836, 2015). "Here we review the findings supporting a role for Tau, spastin and TTLL6 in AD and other tauopathies, HSP and neurodegeneration, and summarize possible therapeutic approaches for AD and HSP." (PMID 26691836, 2015). "Thus, targeting binding of spastin to microtubules, or microtubule polyglutamylation by TTLL1, 5, 6 or 11 could be a therapeutic option not just for AD and other tauopathies, but also for SPAST caused HSP." (PMID 26691836, 2015).
Waardenburg syndrome (1 paper, 2023). A disorder characterized by varying degrees of deafness and minor defects in structures arising from neural crest, including pigmentation anomalies of eyes, hair, and skin. "The only complex-type patient with a SPAST variant also had a SOX10 variant, which is the causative gene in Waardenburg syndrome." (PMID 37251230, 2023).
neurodegenerative disease (15 papers, 2004 to 2025). A disorder of the central nervous system characterized by gradual and progressive loss of neural tissue and neurologic function. "Overexpression of tau protects MTs against the severing action of katanin and spastin, while loss of tau in neurodegenerative diseases, such as Alzheimer’s, indirectly leads to increased spastin activity." (PMID 35865632, 2022). "The miRNA regulation of SPAST also has implications for mutation studies in neurodegenerative disease." (PMID 22574173, 2012). "Mutations in spastin are the most common cause of hereditary spastin paraplegia, a neurodegenerative disease." (PMID 20209135, 2010). "Mutated spastin is the most common cause of HSP, a hereditary, neurodegenerative disease that affects the upper motor neurons." (PMID 40178516, 2025).
cancer (7 papers, 2013 to 2024). A tumor composed of atypical neoplastic, often pleomorphic cells that invade other tissues. "Although the mechanisms are unclear, increased spastin expression resulted in the formation of protrusions and decreased cell proliferation of cancer cell lines." (PMID 26691836, 2015). "Spastin could shift cancer populations from cancer cells showing high proliferation to cells that proliferate less, but show greater malignancy and invasiveness." (PMID 26691836, 2015). "The expression pattern of three corresponding antigens were established in benign and cancer tissue by immunohistochemistry and qPCR: SPAST (Spastin), STX18 (Syntaxin 18) and SPOP (speckle-type POZ protein)." (PMID 26863016, 2016). "SPAST, SPOP and STX18 were found expressed in the epithelium of benign and cancer areas in both patient cohorts." (PMID 26863016, 2016). "Immunohistochemistry and qPCR revealed that SPAST, STX18 and SPOP were expressed in the epithelium of benign and cancer areas of the high and the low inflammation cohorts." (PMID 26863016, 2016). "Additionally, we analyzed the top 100 genes coexpressed with SELENOI across 33 cancer types using GEPIA2.0, and identified PUM2, STRN, WDR43, PRPF40A, and SPAST as highly correlated with SELENOI." (PMID 39669976, 2024).
neurological disorders (7 papers, 2018 to 2025). "Interestingly, mutations in genes involved in the regulation of ER biogenesis and maintenance, such as Valosin-containing protein (VCP), Atlastin-1 (ATL1), Spastin (SPAST), Reticulon 2 (RTN2), and Receptor expression enhancing protein 1 (REEP1) have been linked to neurological diseases." (PMID 29310658, 2018).
tumor (4 papers, 2016 to 2024). "Analysis of protein expression within matched pairs of benign prostate tissue and corresponding tumor areas revealed an increased expression of SPAST and STX18 in most tumor samples whereas SPOP expression remained unchanged." (PMID 26863016, 2016). "Interestingly, tumors derived from endocrine therapy resistant patients (CRPC) were negative for SPAST and SPOP, suggesting loss of these two autoantigens during tumor progression." (PMID 26863016, 2016). "Our findings obtained both in tumor cells and in non-transformed RPE-1 cells show that HIPK2 depletion induces MBR accumulation, whereas depletion of the two known HIPK2 cytokinesis targets, Spastin and ecH2B, has only a marginal effect in MBR accumulation." (PMID 33043004, 2020).
genetic disorder (3 papers, 2012 to 2025). "As a dominant genetic disorder, SPG4 is dosage-sensitive and thus upregulation of the normal SPAST allele could provide therapeutic benefits by preventing or delaying neurodegeneration." (PMID 22574173, 2012).
autosomal dominant disease (2 papers, 2021 to 2024). Autosomal dominant form of disease. "In the most common form of autosomal-dominant disease, the SPG4 (caused by genetic variants in the gene encoding for spastin) is associated with a “pure” phenotype, while, among the autosomal-recessive forms, SPG11 is the most frequent, and associated with a “complicated” phenotype." (PMID 38276084, 2024).